MPO (myeloperoxidase)
Diseases named in the same sentence as MPO in open-access papers (continued):
Sharing a sentence is not in itself a finding about the gene and the disease.
colitis (continued). "Rivastigmine 1 and 2 mg given rectally to rats with colitis induced by rectal administration of 30 mg dintrobezene sulfonic acid (DNBS) also caused a dose related reduction in ChE activity in blood and colon, the number of ulcers and area of ulceration, levels of TNF-α and in MPO activity." (PMID 23469045, 2013). "Similarly, DSS-induced colitis was associated with an increase in colonic neutrophil infiltration and myeloperoxidase (MPO) levels which were not modulated by CS." (PMID 23638007, 2013). "In DSS-induced colitis mice, oral Casein-PE@TNF-Ab markedly increased colon length and suppressed colonic TNF-α, IL-1β, and MPO levels by 82%, 61%, and 62%, respectively, versus DSS." (PMID 41985594, 2026). "To evaluate the effect of curcumin and tryptophan on oxidative stress in DSS-induced colitis, we measured the levels of MDA, MPO and SOD in the colon." (PMID 41010513, 2025). "Colitis induction significantly elevated macroscopic damage scores, stool consistency, inflammatory cytokines, MDA, MPO, and NLRP3, NF-κB, caspase-1, while reducing GSH levels (p < 0.001-0.01)." (PMID 40320895, 2025). "Like I3C, DIM attenuated the DSS-induced colitis by inhibiting TNF-α, IL-6, IFN-γ, IL-10, iNOS, COX-2, NO, PGE2, myeloperoxidase activity (MPO), and NF-kB." (PMID 40094833, 2025). "The apparent contradiction, wherein the antigen alone induced mild inflammatory features (elevated NO, MPO, and edema) while ameliorating TNBS-induced colitis can be reconciled through the immunological concept of inflammatory preconditioning." (PMID 40830617, 2025). "As expected, oxidative stress and lipid peroxidation, indicated by increased levels of MPO and MDA, were elevated following DSS‐induced colitis compared to controls." (PMID 40509652, 2025). "It has been reported that almond polysaccharides can reduce MPO activity and pro-inflammatory factor levels in DSS-induced Colitis mice." (PMID 41008172, 2025). "The activity of myeloperoxidase (MPO) in colonic tissues, which serves as a marker of neutrophil migration to damaged tissue, exhibited a significant increase in the colitis group compared to the control group (p < 0.001)." (PMID 40943092, 2025). "In the betanin supplementation groups, malondialdehyde, myeloperoxidase, TNF-α, IL-1β, mucosal damage, and cell infiltration scores were lower than in the colitis group, while GPx levels were higher." (PMID 41515203, 2025). "Similar reductions in MPO activity have been reported in previous studies involving Spirulina extracts in models of TNBS and DSS-induced colitis." (PMID 41149746, 2025). "The results showed a reduction in MPO expression when T. spiralis larval antigen extract was administered both prior to and subsequent to TNBS-induced colitis." (PMID 40830617, 2025). "The present study evaluated the effect of MPO and PAD4 inhibition in dextran sodium sulfate (DSS)-induced colitis." (PMID 40459411, 2025). "Previous studies have confirmed that OMT can reduce MPO and MDA levels and increase SOD and GSH levels to regulate oxidative stress in colitis mice." (PMID 40370726, 2025). "Herein, we examined the therapeutic potential of two selective enzyme inhibitors: AZD3241 (inhibiting MPO) and GSK484 (inhibiting PAD4) in ameliorating dextran sodium sulphate (DSS)-induced experimental colitis." (PMID 40459411, 2025). "In a DSS‐colitis recovery model, WMP promoted recovery as evidenced by improved weight gain, reduced stool scores, reduced IL‐1β levels, and myeloperoxidase (MPO) activity in colonic tissue." (PMID 40509652, 2025). "Analysis of liver tissue from DSS-induced colitis mice revealed elevated production of pro-inflammatory cytokines, such as IL-1β, IL-6, and TNF-α, along with upregulated LPS and MPO levels." (PMID 40725052, 2025). "Combination therapies significantly ameliorated colitis, reducing DAI, MPO activity, and inflammatory cytokines, while restoring colon length and GLP-1 levels—without inducing liver or kidney toxicity." (PMID 40869234, 2025).
colitis (continued). "Myeloperoxidase (MPO) produces hypohalous acid to carry out its antimicrobial activity and is upregulated in colitis recovered naturally." (PMID 39069899, 2024). "In the colon tissue of mice with colitis, gatifloxacin, LP-HFY11L, and LP-HFY11H all decreased the levels of MPO, NO, and MDA, while the content of GSH increased compared with those in the model group." (PMID 38790796, 2024). "Apigenin treatment inhibited colon damage, MPO activity, and the production of IL-1β, TNF-α, and IL-6 in DSS-induced colitis, as well as the NF-κB and STAT3 pathways in colitis-associated colon cancer tissues in mice." (PMID 39451206, 2024). "For example, inhibition of MPO by both synthetic inhibitors and microbiota-derived indoles have been shown to improve acute dextran sodium sulfate–induced (DSS-induced) colitis." (PMID 39133648, 2024). "In our study, MPO enzyme activity was significantly increased in the colitis-induced group, and DHA application decreased MPO enzyme activity to the levels observed in the control group." (PMID 39105785, 2024). "Oral and rectal administration of cardamonin significantly improved symptoms and histopathological changes in DSS- and TNBS-induced colitis in mice, as evidenced by reduced DAI scores, MPO activity, and colon length shortening." (PMID 39494333, 2024). "MPO-KO and WT mice were subjected to chronic DSS colitis (3 rounds of DSS separated by 16-day equilibration periods)." (PMID 39133648, 2024). "Our previous studies using pharmacological inhibition of MPO in Wt mice improved overall clinical and colon histopathological outcomes during challenge with acute DSS-induced colitis." (PMID 38673843, 2024). "The results showed that ZSS polysaccharide (20 mg/kg) significantly improved the severity of colitis in colitis rats and inhibited the inflammatory response by reducing the activity of TNF-α, IL-1β, IL-6 and MPO in colitis rats." (PMID 39679366, 2024). "Nevertheless, MPO activity was significantly reduced in both ch.colitis/BMS 5 and ch.colitis/BMS 10 groups compared to the ch.colitis group." (PMID 39359253, 2024). "We report that nobiletin treatment attenuates DSS-induced colitis, as indicated by an improved disease activity index, histologic score, and FER, along with a reduction in the level of MPO activity and infiltration of neutrophils in the colon." (PMID 39334888, 2024). "AEEL administration improved bodyweight change, colon shortening, MPO activity, and the albumin content of serum in mice with DSS-induced colitis." (PMID 38612870, 2024). "Consistently, CXCR2 knockout mice exhibited suppressed colonic inflammation during DSS‐induced colitis, with reduced neutrophil infiltration and downregulation of the NET marker MPO." (PMID 39199011, 2024). "NK109 also suppressed the LPS-induced expression of colonic myeloperoxidase, TNF-α, and IL-1β expression, resulting in the attenuation of colitis." (PMID 39203872, 2024). "SE also alleviated LPS-induced myeloperoxidase and TNF-α expression in the colon, resulting in the amelioration of colitis." (PMID 39203872, 2024). "In mouse models of colitis, both walnut protein and its enzymatic products effectively suppressed serum IL-1β, IL-6, TNF-α levels, and myeloperoxidase (MPO) activity, thereby preventing colitis progression." (PMID 39203780, 2024). "The decrease in colonic level of MPO, and more generally an antioxidant effects of EMPA and DAPA were shown in two rat studies in DSS and AA-induced colitis, respectively." (PMID 37086302, 2024). "In the present study, FAS significantly increased the levels of CAT, T-AOC, and T-SOD, and inhibited the levels of MDA, MPO, and ALT in DSS-induced colitis mice." (PMID 39274922, 2024). "Combined administration of SM and nano Se can improve anti-inflammatory and antioxidant capacity by reducing the expression of TNF-α, IL-1β, NF-κB, MPO, lipid peroxidation and protein carbonyl, finally relieve symptoms of TNBS-induced colitis." (PMID 37033644, 2023).
colitis (continued). "MDA and MPO activities, on the other hand, accumulated abnormally in DSS-induced colitis; however, this situation was suppressed after miR-200a intervention." (PMID 37646040, 2023). "Here, we demonstrated that the concentrations of MDA and MPO increased and CAT decreased in mice with colitis." (PMID 36766197, 2023). "Thymol exhibits the ability to attenuate increased MPO and MDA levels induced by LPS, as well as the expression of NF-κB, in a murine model of acute lung injury and in colonic homogenates in murine colitis." (PMID 37701897, 2023). "During the experimental treatment period, we assessed changes in weight and disease activity index (DAI), quantified the intestinal index, and determined myeloperoxidase (MPO) activity and reactive oxide species (ROS) levels in colitis mice." (PMID 38018589, 2023). "In our study, L. plantarum AR113 relieved the symptoms of DSS-induced colitis in mice by reducing DAI values, inhibiting the hyperactivated MPO activity, and increasing the colon length, but the bsh 1 or bsh 3 knockout strains did not." (PMID 36895642, 2023). "S. boulardii CNCMI-745 and S. cerevisiae QHNLD8L1 administration significantly inhibited the increase in MPO and iNOS activities, indicating that they promoted inflammatory remission in mice with DSS-induced colitis." (PMID 37047694, 2023). "Cur-AceKGM NPs can decrease the colon local level of MPO and DAI score, significantly alleviate the symptoms of colitis." (PMID 37033644, 2023). "Significant disparities in inflammation were observed between the treatment groups and placebo group in acute colitis models when having a gavage of Flavo-Natin at a dose of 3 mg/day, as assessed by MEICS, histological score, MPO activity, and cytokine levels." (PMID 38003220, 2023). "These polysaccharides reduced myeloperoxidase (MPO) activity, levels of pro-inflammatory cytokines and NO levels in mice with colitis." (PMID 37888459, 2023). "In murine colitis, melatonin reduces the generation of ROS and reactive nitrogen species (RNS), characterized by lowering colonic MDA levels and MPO activity and improved antioxidant defenses with increased GSH and SOD levels in the colon." (PMID 37701897, 2023). "The MPO activity was significantly increased in DSS-induced colitis mice compared with control mice, while PHI (25, 50, and 100 mg/kg, P < 0.01) or MES (100 mg/kg, P < 0.01) treatment significantly suppressed MPO activity." (PMID 36768559, 2023). "Curcumin has been shown to decrease OS markers MPO and MDA levels and cell apoptosis in different animal models of colitis." (PMID 37701897, 2023). "Oral administration with apigenin alleviated colon length shortening, decreased levels of colonic myeloperoxidase (MPO), alkaline phosphatase (AKP), TNF-α, IL-6, and restored intestinal microbiome in TNBS and DSS colitis models." (PMID 37298531, 2023). "In this study, we proved that BAA6 played a protective role in the colitis induced by DSS as indicated by deceased DAI and the histological score, attenuated MPO activity, and mucosal damage." (PMID 36789079, 2023). "FA treatment significantly decreased the MPO/DNA signals in neutrophils from DSS colitis mice, indicating that FA mitigates DSS-induced colitis, at least in part, through inhibition of NETs formation." (PMID 37813835, 2023). "In contrast, several studies investigating hepatic tissue in colitis induction models with 3%, 4%, and 5% DSS reported increased levels of TNF-α and/or MPO activity and similarly to our work reduced levels of IL-10." (PMID 37577725, 2023). "The β-carotene treatment significantly reduced myeloperoxidase (MPO) activity and the levels of IL-17, IL-6, TNF-a, and COX-2 inflammatory markers in the colon of mice with DSS-induced colitis." (PMID 38250921, 2023). "The 7th day colitis group had higher macroscopic damage scores, wet weight, and myeloperoxidase activity and lower basal TER than the sham, 14th day colitis, and 28th day colitis groups." (PMID 37909497, 2023).
colitis (continued). "In comparison to the controls, mice with TNBS colitis and H4R knockout expressed higher levels of chemokines CXCL1 (KC) and CXCL2 (MIP2), IL-6, and the neutrophil enzyme myeloperoxidase (MPO)." (PMID 37373085, 2023). "This study evaluated the ameliorative effects of PEG-CNPs on TNBS-colitis using several indicators, including body weight, DAI, colon length, MPO activity and histological analysis." (PMID 37507801, 2023). "Meanwhile, the correlation analysis showed that Alistipes was negatively correlated with MPO and CD4+CD45+CCR7+ and CD4+CD45+CCR7+ cells when experimental colitis was treated with COG." (PMID 35832382, 2022). "Second, COG can markedly decrease MPO to inhibit neutrophil infiltration or reduce MDA to suppress lipid peroxidation in experimental colitis induced by DSS." (PMID 35832382, 2022). "Moreover, a recent study suggested that Didymin treatment significantly attenuated the MPO activity and neutrophil infiltration and converted pro-inflammatory M1-like to the anti-inflammatory M2-like macrophage phenotype, thereby alleviating the clinical symptoms of colitis." (PMID 35154128, 2022). "The effects of roflumilast on colonic levels of MPO, MDA, and GSH in rats with trinitrobenzenesulfonic acid (TNBS)-induced colitis (n=8)." (PMID 35239781, 2022). "Consistent with previous studies, our results indicated that GTP inhibited the activity of NF-κB and MPO, the expression of TNF-α, IL-1β, IL-6, iNOS, and COX-2, and the production of NO and PGE2 in colon tissues of mice with DSS-induced colitis." (PMID 35807865, 2022). "The results showed that L. gasseri JM1 alleviated DSS-induced colitis in mice, with reductions in disease activity index (DAI), histological scores and myeloperoxidase activity as well as alleviation of colonic shortening." (PMID 36615796, 2022). "The TNBS-induced colitis rats showed significant increases in disease activity scores, serum TNF-α, IL-2, and IL-6 levels, and colonic myeloperoxidase and malonaldehyde content." (PMID 35239781, 2022). "In parallel, the reduced MPO activities in the colon were observed following BUR pretreatment, indicating the beneficial effects of BUR in the remission of colitis." (PMID 36290717, 2022). "Its impact on colitis was evidenced by improving the biochemical markers TAC and GSH and the decrease in IL-1β, TNF-α, MDA, and MPO compared to the colitis control group." (PMID 35428860, 2022). "Further studies uncovered that PYY 3–36 treatment reduced the levels of colon myeloperoxidase (MPO) and both colonic and systemic TNF-α and IL-6 observed in murine colitis." (PMID 35443853, 2022). "In acetic acid-induced colitis of Sprague–Dawley rats, nicotine (1 mg/kg, i.p.)reduced the extent of colonic lesions, colonic malondialdehyde (MDA) level, MPO activity, NF-κB expression, and serum IL-1β level." (PMID 35251010, 2022). "The results showed that the SOD level in the colon tissue of the colitis mice was significantly reduced compared with the normal control group (P < 0.05), while the MDA and MPO levels were significantly increased (P < 0.05)." (PMID 35346043, 2022). "The results of established colitis treatment showed that the neutralization of TNF-α by the antibody generated a reduction in CD68 and myeloperoxidase (MPO) markers, indicating a reduction in macrophages and neutrophils in the colon tissue." (PMID 35939430, 2022). "Cranberry polysaccharide has been shown to lower the macroscopic score and damage area of the colon, down regulate MPO and MDA, greatly stimulate mucosal repair and regeneration, and diminish experimental colitis produced by DSS and TNBS." (PMID 35860025, 2022). "Myricetin can reduce the content of MPO and MDA by decreasing the production of NO, increasing the SOD and GSH expression, and exerting antioxidant effects in DSS-induced colitis." (PMID 35873579, 2022).
colitis (continued). "In our investigation, MPO and MDA levels were shown to be elevated in the colon tissue of the colitis control group, whereas GSH levels were found to be decreased." (PMID 35428860, 2022). "Naringin can reduce the inflammatory response in colonic tissues by upregulating the levels of SOD and GSH, reducing the levels of MDA and MPO, thus improving the TNBS-induced pathological changes in colitis." (PMID 35873579, 2022). "Our results showed that central administration of HO attenuated DSS-induced colitis, as indicated by the reduction of disease activity index (DAI) scores, macroscopic scores, histological scores, and the myeloperoxidase (MPO) activity." (PMID 36176442, 2022). "Then, the following were assessed: the colitis activity score, tumor necrosis factor (TNF)-α, interleukin (IL)-2, and IL-6 serum levels, colonic length, and myeloperoxidase, malonaldehyde, and glutathione levels." (PMID 35239781, 2022). "BUR pretreatment significantly decreased the MPO activity of colon, confirming the anti−inflammatory effects of BUR in DSS−induced colitis." (PMID 36290717, 2022). "For instance, treatment with geraniol significantly opposed the TNBS-induced colitis effects on the inflammatory parameters, including NFκB, PGE2, IL-1β, ICAM-1, and MPO." (PMID 36009287, 2022). "Sinapic acid reduces diarrhea in colitis-induced murine models, reducing TNF-α and myeloperoxidase production." (PMID 35056616, 2022). "After colitis mice received Nec-1 treatment, their SOD levels increased, and MDA and MPO levels decreased." (PMID 35346043, 2022). "The pharmacological evaluation showed that FMPs attenuated inflammation in AA-induced colitis by reducing the serum concentrations of TNF-α, IL-6, IL-8, and IL-10 and the colonic concentrations of MPO, MMP9, and CXCR1." (PMID 35620404, 2022). "We next examined the level of myeloperoxidase (MPO) in serum, finding it was significantly higher in DSS-induced colitis mice than the control group, whereas the high dosage of MOP intervention reversed this abnormal change." (PMID 35911761, 2022). "Meanwhile, compared to mice with colitis, COG-treated mice showed lower levels of MDA, MPO, NO, and eNOS and higher levels of GSH-Px and MAO, which indicated that oxidative stress damage in colitic mice was alleviated by COG." (PMID 35832382, 2022). "Plumericin reduced the activity of myeloperoxidase, inhibited the expression of ICAM-1, P-selectin, and the formation of PAR, and reduced apoptosis parameters in mice colitis induced by DNBS." (PMID 33445622, 2021). "The MPO concentration was increased by DSS and reversed by Ala-Gln, indicating that Ala-Gln has alleviated colitis inflammation." (PMID 34046146, 2021). "Increased MPO activity and higher levels of pro-inflammatory factors (TNF-α, IL-1β, and INF-γ) in colitis were significantly reversed by naringin." (PMID 34504431, 2021). "As neutrophils play a crucial role in the pathogenesis of colitis and infiltrate the colon tissues in UC, MPO levels were dramatically increased in the CsAc- and CsAc-AMP-treated and untreated colitis groups when compared with that in the healthy group." (PMID 34575488, 2021). "Our study found that TNF-a, IL-6, NO, MPO, and MPA levels increased in the colitis group and decreased after antioxidant therapy." (PMID 34912469, 2021). "In acetic acid-induced acute colitis in mice, TSG (60, 120 mg/kg) significantly ameliorated the colonic injury by reducing the levels of myeloperoxidase (MPO), malonaldehyde (MDA) and NO as well as increasing superoxide dismutase (SOD) activity." (PMID 35069206, 2021). "Exposure to RS led to colon shortening, induced myeloperoxidase activity and NF-κB activation (p-p65 to p65 ratio), and increased TNF-α and IL-6 expression in the colon, leading to the outbreak of colitis." (PMID 34391441, 2021). "Expression of occludin and MPO was significantly decreased and increased, respectively, in DSS colitis mice." (PMID 34681392, 2021).